NLRP3 (NLR family pyrin domain containing 3)
Diseases named in the same sentence as NLRP3 in open-access papers (continued):
Sharing a sentence is not in itself a finding about the gene and the disease.
infection (continued). "Further, the accumulated capsular strains induce the secretion of pro-inflammatory cytokines through various signaling pathways, such as TLR4 or NLRP3, ultimately leading to irreversible organic damage, just like the lung tissues of K7-challenged mice at 48 h after infection." (PMID 31191500, 2019). "Activated NLRP3 by infection or various stress induces apoptosis-associated speck-like protein containing a caspase activation and recruitment domain (CARD) domain (ASC), and then NLRP3 inflammasome is formed in combination with activated caspase-1 precursor." (PMID 31731792, 2019). "Moreover, these analyses revealed that MLN from MNV-infected Stat1-/-Nlrp3+/- mice also displayed Nlrp3-dependent GSDMD cleavage after MNV infection, indicative of pyroptosis." (PMID 31017981, 2019). "Therefore, the activation of NLRP3 inflammasome in M1 macrophages plays an important role in the response to infection and the pathogenesis of tissue insult." (PMID 32118052, 2019). "Furthermore, it has been described that in vitro DENV-infection of macrophages induces an inflammatory response through activation of the NLRP3 inflammasome, leading to the release of IL-1β." (PMID 30901375, 2019). "These cytokines are produced upon infection in a NLRP3- and Caspase1/11-dependent manner." (PMID 31479495, 2019). "In the current study, we addressed whether the NLRP3 inflammasome contributed to acute lung injury, innate immune cell activation, and lung repair during infection with N. brasiliensis." (PMID 31586037, 2019). "Notably, whereas AdWT infection blocked NLRP3 inflammasome activity compared to uninfected cells, infection with a replication defective AdEasy vector appeared to potentiate the release of IL-1ß and HMGB1 compared to uninfected cells." (PMID 31849970, 2019). "Finally, we demonstrated that the CHIKV in vitro infection of murine bone marrow-derived macrophages induced IL-1 beta production in a mechanism that is significantly dependent on the inflammasome NLRP3 activation." (PMID 31211814, 2019). "Interestingly, Stat1-/-Gsdmd-/- mice phenocopied the statistically significant survival advantage of Stat1-/-Nlrp3-/- mice upon gastrointestinal MNV infection when compared to Stat1-/- mice." (PMID 31017981, 2019). "In addition, Stat1-/-Gsdmd-/- and Stat1-/-Nlrp3-/- mice showed diminished fecal Lcn-2 levels upon gastrointestinal MNV infection." (PMID 31017981, 2019). "The NLRP3 inflammasome is a multiprotein platform that is activated upon cellular infection or stress and subsequently leads to caspase-1-dependent secretion of proinflammatory cytokines, such as IL-1β and IL-18, and an inflammatory form of cell death termed as pyroptosis." (PMID 31222000, 2019). "It was therefore important to assess whether elevated granulocytic responses in Nlrp3−/− mice impacted the resolution of inflammation and repair of lung tissue damage during the later stage of the infection model." (PMID 31586037, 2019). "Similarly, active caspase-1, mature IL-1β, and secondsreted IL-1β were induced by infection with either E. coli or P. mirabilis, and this induction was reduced by NLRP3 knockdown." (PMID 30823406, 2019). "The NLRP3 inflammasome is a multiprotein complex that activates caspase-1 during infection and ROS." (PMID 30779706, 2019). "The NLRP3 inflammasome was viewed as a likely candidate since earlier studies showed that treatment with the danger signal, extracellular ATP, and infection with the periodontal pathogen Fusobacterium nucleatum could activate the NLRP3 inflammasome in GECs." (PMID 30956972, 2019). "To further investigate the LRV-inhibition of the NLRP3 inflammasome in human cells, we measured IL-1β and Casp1 p20 in response to L.g.− and L.g.+ infection in cells treated with KCl (which impairs potassium efflux and activation of NLRP3) or Poly:IC (TLR3 agonist)." (PMID 31754185, 2019). "Infection with VSV or EMCV generates NLRP3 inflammasome activation and ensuing IL-1β release." (PMID 31024004, 2019).
infection (continued). "In addition, we found that CSFV at a relatively high infection dose (MOI = 1) had an inhibitory effect on the NLRP3 and ASC proteins." (PMID 30013955, 2018). "Taking into account that during the acute infection with the Tulahuen strain, the liver of B6 mice displays cellular infiltrates with predominance of macrophages, we decided to analyze the induction of NLRP3 inflammasome and IL-1β within these cells." (PMID 29774028, 2018). "NLRP3 inflammasomes are activated by damage, inflammation, or stress, and this activation leads to the production of active IL-1β and IL-18 by activating caspase I in IAV infection, while NLRP3 can activate the production of cytokines by triggering signal 1 and signal 2 during infection with IAV." (PMID 29734779, 2018). "It has been confirmed in the hamster model for CL that infection by Leishmania generates the activation of the Nlrp3 inflammasome with the subsequent production of IL1β, and this cytokine may negatively regulate the expression of PDGF." (PMID 30333964, 2018). "To determine if activation of the NLRP3 inflammasome occurred in aorta endothelial cells stimulated with H. parasuis, and to explore the molecular mechanisms mediating inflammasome activation, we established an H. parasuis cell-infection model." (PMID 29339754, 2018). "For example, EseG is involved in microtubule depolymerization, EseJ helps E. piscicida proliferate in the cell, EseH inhibits MAPK activation via phosphothreonase activity to promote infection, and EvpP promotes bacterial colonization by inhibiting NLRP3 inflammasome activation." (PMID 29503811, 2018). "Therefore, the diminished fungal loads observed at weeks 6 and 10 post-infection have possibly triggered diminished macrophages and dendritic cells NLRP3 activation and reduced IL-1β production." (PMID 30410119, 2018). "Therefore, it seems that IL-1β production through ATF3-mediated ROS inhibition is necessary to prevent the inhibition of primed NLRP3, as a sufficient amount of ROS was secreted during infection in the case of gram-positive bacteria." (PMID 30214444, 2018). "The suppression of NLRP3 inflammasome activity by mitochondrial fission was reported in a human lung cell line in response to the mouse-adapted IAV PR8 strain during the late phase of infection." (PMID 30096906, 2018). "Taken together, these results suggest that macrophages and cDCs are not required for early IFN-α/β cytokine production (within the first 24 h of infection), but have indispensable roles at the late stage (after 24 h of infection) of YM infection in Nlrp3−/− and Aim2−/− mice." (PMID 30470758, 2018). "In this study, we detected NLRP3 inflammasome activation in five organs, the kidney, liver, lung, spleen and testis, further confirming that T. pallidum induced systemic inflammatory during infection." (PMID 29490620, 2018). "Release of IL-1β was dependent on both LPS pretreatment and infection, consistent with the two-step hypothesis for NLRP3 inflammasome activation." (PMID 30154263, 2018). "Indeed, activation of the NLRP3 inflammasome amplifies inflammation and promotes pathogen infection via a process involving triggering of T helper 2-biased adaptive immune responses or secretion of secondary danger-associated molecular pattern molecules." (PMID 30087667, 2018). "NLRP3 expression was significantly upregulated after infection with TMEV in all cell types tested (i.e., bone marrow-derived dendritic cells, neonatal brain cells, and neonatal oligodendrocytes) derived from susceptible SJL mice but not in cells derived from resistant B6 mice." (PMID 28445497, 2017). "Interestingly, in an EV-A71 infection mouse model, viral proteases were able to overcome the effects of NLRP3 inflammasome activated IL-1β leading to increased viral replication." (PMID 28724943, 2017). "NLRP3 expression in these animals thus appears linked to the infection-triggered inflammatory response as opposed to the inflammatory response to thermal injury." (PMID 28943993, 2017).
infection (continued). "We conclude that P2X7 receptor activation inhibits T. gondii growth via ROS generated, most likely, from NADPH oxidase (rather than mitochondrial ROS), while also activating the canonical NLRP3 inflammasome, which leads to IL-1β secretion and infection control via mitochondrial ROS production." (PMID 29075257, 2017). "Finally, we showed using a murine CBM model that F. pedrosoi elicits a NLRP3-regulated IL-1β and interleukin-18 release in vivo, but without NLRP3 inflammasome activation interfering in the course of the experimental infection." (PMID 29209318, 2017). "Total RNA from control siRNA and NLRP3 siRNA transfected CD14+ monocytes was used for the detection of ZIKV copies at 72 h post-infection, which showed a significantly reduced viral copies in NLRP3 siRNA transfected monocytes as compared to the control siRNA transfected cells." (PMID 29167459, 2017). "Interestingly, an increased influx of GR1+Ly6G+ PMN cells was seen in the lungs of WT mice in comparison with Nlrp3−/−, Casp1/11−/−, and Asc−/− mice at 48 h, 2 and 4 weeks of infection." (PMID 28740491, 2017). "Furthermore, it is demonstrated that inhibition of NLRP3 inflammasome significantly alleviates the liver inflammation and collagen deposition that are induced by infection with S. japonicum." (PMID 28808303, 2017). "In physiological conditions, the inflammasome pathway is activated in response to dangerous situations provoked by infections, tissue injury, or cellular stress, being the inflammasome formed by the sensor NLRP3 the most promiscuous inflammasome pathway activated in many different situations." (PMID 28191008, 2017). "Neutrophil numbers remained high in these mice at day 1 post-infection, but declined at later time points, while the magnitude of the macrophage response, although higher at day 3, is similar to those seen in wildtype and Nlrp3-/- mice infected with Ft LVS." (PMID 27926940, 2016). "Mice lacking components of the NLRP3- or NLRC4- inflammasome have been found to be more susceptible to infection by various bacterial pathogens." (PMID 27617233, 2016). "Importantly, lung necrosis is already moderated at 3 days post-infection in Nlrp3-/- mice, at which point bacterial numbers in the lung also appear to be declining." (PMID 27926940, 2016). "Deciphering whether Nlrp3 is required for the apoptotic cell death observed during infection with the Type A strain SchuS4, a caspase-3 independent mechanism, or both, will be of considerable interest and require further study." (PMID 27926940, 2016). "It is currently unknown whether the MAC triggers NLRP3 and IL-1β activation to defend against infection in liver recipients." (PMID 27063552, 2016). "Dissection of the contributions of the cellular compartments has revealed that cecum-derived E-cadherin+ intestinal epithelial cells (IEC) express high amounts of ASC adaptor, and Nlrp3 and Nlrc4 activation are both critical for protection against C. rodentium early in the course of infection." (PMID 27617233, 2016). "Consistent with our hypothesis, HGF infection with HGPg induced MOI-dependent NLRP3 gene expression." (PMID 28083517, 2016). "Since IL-17 levels increase concomitantly with the appearance of neutrophils in the lungs of Nlrp3-/- mice at 1 dpi, IL-17 may be negatively regulated by Nlrp3 early during infection." (PMID 27926940, 2016). "This IL-1β production in response to infection with KIM5 ΔYopK was eliminated in NLRP3/NLRC4 deficient cells, but was independent of Pyrin." (PMID 27911947, 2016). "Although the connections between hyperglycemia and inflammation have been extensively characterized, the molecular mechanisms responsible for NLRP3 expression after infection with P. gingivalis cultured under HG conditions remains unclear." (PMID 28083517, 2016). "Interestingly, IL-1β production was significantly reduced following Ft LVS or SchuS4 infection of cells from Nlrp3-/- mice." (PMID 27926940, 2016).
infection (continued). "However, the in vivo response of Nlrp3-/- mice to infection with the Ft LVS or SchuS4 strain, most relevant to human disease, is essentially unexplored." (PMID 27926940, 2016). "However, at later times after infection, the Nlrp3 response mounted by macrophages appears to be indispensable for reducing the severity of the histopathology." (PMID 27617233, 2016). "Surprisingly, a large percentage (~50%) of Nlrp3-/- mice survived lethal LVS infection." (PMID 27926940, 2016). "The selectivity of the fenamates to NLRP3 over other inflammasomes reported here is another advantage since their use would avoid compromising NLRC4 or AIM2 inflammasome-dependent host responses to infection." (PMID 27509875, 2016). "Having said that patient DCs possess an enhanced basal expression of NLRP3 and the unresponsiveness to a subsequent infection might be due to the saturation in NLRP3 gene levels or due to a chronic inflammatory state of these cells." (PMID 27994587, 2016). "NLRP3 also seeds inflammasome formation, but is activated by a wide array of stimuli and likewise can promote pyroptotic and Asc-dependent, but Caspase-1-independent (pyronecrotic) death of myeloid cells during infection." (PMID 27926940, 2016). "Indeed, NLRP3 was significantly increased in murine and human CF cells and its inhibition ameliorated inflammatory pathology in murine experimental infections and attenuated IL-1β production in human CF cells." (PMID 26972847, 2016). "To further confirm LM mainly activates NLRP3 inflammasome, we used wild-type and NLRP3−/− B6 cells to analyze the IL-1β release and caspase-1 activation upon LM infection (ATP and poly (dA:dT) were used as the NLRP3 and AIM2 inflammasome activators, respectively)." (PMID 26911557, 2016). "IL-1β, which also signals via MyD88, has been proposed to be dispensable for host defense as mice deficient in the Nlrp3 inflammasome did not exhibit increased susceptibility to S. pyogenes in an intraperitoneal infection model." (PMID 25756897, 2015). "Our infection experiments with L. major and L. mexicana revealed an attenuated capability of macrophages to produce and secrete IL-1β when stimulated with the specific and well characterized NLRP3 inflammasome agonist HZ." (PMID 26114647, 2015). "In the later stages of infection, other inflammasomes, such as NLRP3, activated by commensal bacteria, may play a more important role in the regulation of mucosal IL-1β." (PMID 26269452, 2015). "Because infections with NleA-producing bacteria reduced the de-ubiquitination of NLRP3 compared with that of the NleA-negative bacteria, it is likely that NleA binds to ubiquitinated NLRP3 and inhibits de-ubiquitination." (PMID 26332984, 2015). "Given that NleA reduces the de-ubiquitination of NLRP3 during infection and that NleA binds to ubiquitinated NLRP3 in a co-immunoprecipitation assay, we speculated that NleA could inhibit the de-ubiquitination of NLRP3 upon stimulation." (PMID 26332984, 2015). "In addition, NLRP3 was significantly up-regulated after pre-incubation with ATP for 3 h then infection with P. gingivalis and stimulation with P. gingivalis LPS for 2 h, but was down-regulated at 4 h." (PMID 26511096, 2015). "Taken together, these results showed that NleA specifically targets NLRP3 inflammasome activation eliciated by infection and that the effector prevents the assembly of the NLRP3 inflammasome, possibly through interfering the change of ubiquitination in NLRP3 during infection." (PMID 26332984, 2015). "Interestingly, the expression of NLRP3 was also rapidly increased and remained elevated until 4 h of infection." (PMID 26683708, 2015). "Live non-pathogenic and pathogenic Escherichia coli are known to elicit the NLRP3 inflammasome, and such activation has been shown to be essential for clearance of Citrobacter rodentium, a mouse model pathogen of EPEC, in an animal infection model." (PMID 26332984, 2015).
infection (continued). "In the murine typhoid model, in which mice were not pretreated with streptomycin prior to oral inoculation with S. Typhimurium, equal bacterial counts were seen in WT, Asc−/− and Nlrp3−/− mice after infection in all organs (MLNs, liver, spleen, blood) at all time points." (PMID 25115174, 2014). "In the lung, expression level of NLRP3 increased after infection compared with the control." (PMID 25547136, 2014). "Thus, it would be worth testing the role of NLRP3 in Chagas disease cardiomyopathy and not only relative to infection." (PMID 25412247, 2014). "It is also plausible that the differences in the source of mφs, parasite isolates, and the time course of infection may explain the observed differences in the ability of NLRP3-/- mφs to control T. cruzi infection in our and published studies." (PMID 25372293, 2014). "However, Shigella was also shown to induce macrophage cell death via Nlrp3 after 2–6 hrs of infection at a bacteria/macrophage ratio of 50∶1." (PMID 24516390, 2014). "Thus, while conserved bacterial peptidoglycan fragments are initially recognized by receptors NOD1 and NOD2, the perturbations inflicted over the course of infection can activate NLRP3." (PMID 25254654, 2014). "In contrast, our study showed that infection of wild-type and NLRP3 knockout macrophages but not NLRC4-deficient macrophages with B. pseudomallei E8 leads to activation of caspase-1 and downstream signalling pathways at 1.5 hours after infection." (PMID 24626296, 2014). "It was therefore hypothesized that Nlrp3−/− (and Asc−/− mice especially), having lower levels of inflammasome-processed cytokines, would succumb earlier to infection with S. Typhimurium." (PMID 25115174, 2014). "Although OBs have been shown to express NLRP-3 required for caspase-1 activation associated with OB death in response to infection, we find that MSU activates NLRP3 in human OBs with no production of pro-IL-1β or IL-1β." (PMID 24456929, 2013). "To characterize the mechanism underlying the IL-1β response in NHBE cells, we measured receptor transcript levels; we also assessed the efficiency of specific knockdowns of TLR3, RIG-I, and NLRP3 in primary NHBE cells at 13 h post-infection (time of peak transcriptional response to IAV)." (PMID 23592984, 2013). "As TRAIL and NLRP-3 activation require active infection of the host cell, these findings indicate that a separate mechanism may be involved in activating apoptosis in osteoblasts following exposure to soluble factors produced by biofilms." (PMID 23767824, 2013). "Interestingly, when we conducted infections in Nlrp3 KO BMDCs, we found minimal reduction in IL-1β levels compared to WT BMDCs; our observations suggests that C. difficile has the capacity to engage other, as yet unidentified NLRs during BMDC activation." (PMID 23922820, 2013). "On the other hand, Nlrp3−/− macrophages slightly altered IL-6 levels after infection with the L.p." (PMID 24058709, 2013). "The activation of the Caspase-11/NLRP3 non-canonical inflammasome during infection was evident when examining Caspase-11- and TRIF-deficient mice, which were both more susceptible for C. rodentium infection." (PMID 24381573, 2013). "Infection of macrophages or dendritic cells deficient in NLRP3 with Mtb does not induce secretion of IL-1β or IL-18." (PMID 24130966, 2013). "Several in vivo infection models have highlighted the central role of NLRP3 in host defense." (PMID 24312100, 2013). "ATP may be released upon infection or other danger stimulation, and extracellular ATP may then become an alarm signal that can initiate innate immunity, likely by activating the NLRP3 inflammasome." (PMID 23717478, 2013). "In addition, mutants lacking FLT_0325 also induce higher levels of caspase-1 activation dependent on Aim2 and Tlr2 and secretion of IL-1β dependent on Tlr2, Aim2, and Nlrp3 in the early periods of infection." (PMID 24324933, 2013).